DNM1L (dynamin 1 like)
Diseases named in the same sentence as DNM1L in open-access papers (continued):
Sharing a sentence is not in itself a finding about the gene and the disease.
gallbladder cancer (1 paper, 2025). "In gallbladder cancer, USP3 stabilizes DNM1L by deubiquitination, inhibiting its proteasomal degradation." (PMID 41301681, 2025).
Hemiparesis (1 paper, 2024). Loss of strength in the arm, leg, and sometimes face on one side of the body. "The proband has a previously undescribed clinical manifestation, namely hemiparesis, which may be an additional feature of the growing phenotypic spectrum of DNM1L-related diseases." (PMID 38341530, 2024).
Hepatic fibrosis (1 paper, 2025). The presence of excessive fibrous connective tissue in the liver. "Liver-specific Dnm1l-KO (L-Dnm1l-KO) mice showed increased alanine aminotransferase levels and hepatic fibrosis, with spontaneous liver tumors developing by 12 to 18 months of age." (PMID 41401035, 2025).
hypertrophic cardiomyopathy (1 paper, 2025). A condition in which the myocardium is hypertrophied without an obvious cause. "As for the hypertrophic cardiomyopathy (HC), which was the cause of death of our patient, it was reported in one of the two patients with the p.(Gly401Ser), in other three patients with a DNM1L pathogenic variant in the MD and in one patient with a pathogenic variant in the GTPase domain." (PMID 39859560, 2025).
leukemia (1 paper, 2020). A malignant (clonal) hematologic disorder, involving hematopoietic stem cells and characterized by the presence of primitive or atypical myeloid or lymphoid cells in the bone marrow and the blood. "Interestingly, a survey on the Leukemia MILE Dataset shows that T-ALL primary cells express lower mRNA levels of Bcl2l11 (Bim) compared with healthy bone marrow control tissue while Dnm1l (Drp1), Opa1 and Bcl2 levels do not vary." (PMID 32346136, 2020).
liver cancer (1 paper, 2023). An epithelial or non-epithelial malignant neoplasm that arises from the liver. "A risk model based on the ICD-related genes PRNP, DNM1L, and CASP8 was developed to predict the prognosis of liver cancer." (PMID 37361216, 2023).
MERRF (1 paper, 2021). A mitochondrial encephalomyopathy characterized clinically by a mixed seizure disorder, myoclonus, progressive ataxia, spasticity, and a mild myopathy. "Consecutive MRIs were performed in 17 patients and imaging evidence of disease progression was present in 11 patients [six patients with MELAS, two patients with POLG1, and the patients with MERRF, exosome component 3 (EXOSC3), and dynamin-like protein 1 (DNM1L)]." (PMID 34912288, 2021).
nasopharyngitis (1 paper, 2020). An inflammatory process that affects the nasopharynx. "NPC tumor tissues exhibited relatively high DNM1L mRNA expression compared to nasopharyngitis tissues." (PMID 32433544, 2020).
oral cancer (1 paper, 2023). "To understand the connection between MTFP1-induced mitochondrial fission and mitophagy in oral cancer cells, we studied mitophagy in DNM1L deficient cells expressing MTFP1 and found that MTFP1 controls mitochondrial fission during CCCP (carbonyl cyanide m-chlorophenylhydrazone)-induced mitophagy." (PMID 40395309, 2023). "Thus, we examined cell death programs in MTFP1-overexpressing oral cancer cells treated with cisplatin in the presence of wortmannin, a PI3K inhibitor, and Mdivi1, a DNM1L inhibitor that also blocks MTFP1-induced mitophagy." (PMID 40395309, 2023).
pulmonary fibrosis (1 paper, 2021). Chronic progressive interstitial lung disorder characterized by the replacement of the lung tissue by connective tissue, leading to progressive dyspnea, respiratory failure, or right heart failure. "It has been reported that AX can prevent pulmonary fibrosis by promoting myofibroblast apoptosis through dynamin-1 like protein (Drp1)-mediated mitochondrial fission." (PMID 35010981, 2021).
serous ovarian cancer (1 paper, 2024). "According to TCGA data the DNM1L gene is amplified in >50% serous ovarian cancer cases (5% high level amplification, 46% low level gain), while only 7% of cases show heterozygous loss." (PMID 39191946, 2024).
ZIKV infection (1 paper, 2020). "Mdivi-1, the mitochondrial fission inhibitor targeting DNM1L, also blocked mitochondrial fragmentation and cell death caused by ZIKV infection." (PMID 33424801, 2020). "To further explore if blocking mitochondrial fragmentation would help increase cell survival after ZIKV infection, we over-expressed both MFN1 and MFN2 to restore normal fusion and treated cells with Mdivi-1 to inhibit DNM1L activity, reducing mitochondrial fission." (PMID 33424801, 2020).
tumor (36 papers, 2016 to 2025). "We show that alternative splice variants of the fission protein Drp1 (DNM1L) contribute to the complexity of mitochondrial fission/fusion regulation in tumor cells." (PMID 39191946, 2024). "Mitochondrial fission caused by the overexpression of DNM1L is demonstrated to be positively regulated by the activation of oncogenic mutations and correlated with accelerated tumor progression, resistance to chemotherapy, and metabolic deregulation." (PMID 38238834, 2024). "Differential analysis showed that six tumor-infiltrating immune cells were associated with DNM1L expression, whereas correlation analysis showed that seven tumor-infiltrating immune cells were associated with DNM1L expression." (PMID 39507763, 2024). "Therefore, changes in DNM1L expression are closely associated with tumor generation and progression." (PMID 39507763, 2024). "In vivo, DNM1L overexpression increases subcutaneous tumor volume by −50% and markedly elevates hepatic metastatic nodules, whereas DNM1L knockdown reduces metastatic foci by at least half, identifying DNM1L as a key driver of GBC liver metastasis." (PMID 41301681, 2025). "Even in the junctional region, DNM1L was still overexpressed in the tumor region as compared with the normal region." (PMID 39507763, 2024). "The results of this study will reveal the important role of DNM1L in GC and suggest a potential relationship between DNM1L and tumor immune infiltration." (PMID 39507763, 2024). "Specifically, targeted inhibition of the DNM1L/DRP1-FIS1 axis demonstrated significant anti-tumor effects, whereas inhibiting MFF expression exhibited notable pro-tumor effects." (PMID 39350223, 2024). "The OCR/ECAR, an indicator of tumor cell preference for glycolysis, increased following DNM1L up-regulation and decreased upon sh-FIS1." (PMID 39350223, 2024). "The analysis revealed that the relative expressions of PTGS2 and DNM1L were remarkably upregulated in HCC tumor tissues (n = 240) compared with normal samples (n = 193)." (PMID 35159089, 2022). "We identified that OPA1, MFN1, and DNM1L were significantly increased in both NSCLC tumor tissues (P < 0.05)." (PMID 36573240, 2022). "In our study, we found that DNM1L was highly expressed in tumor tissues, while Fis1 was low expressed." (PMID 36573240, 2022). "Fusion-related (OPA1, MFN1) as well as fission related (DNM1L) genes were found to be increased in the basal-like subtype when compared to Luminal A tumor samples." (PMID 31231612, 2019). "The proportion of tumor-infiltrating immune cells was analyzed using the CIBERSORT algorithm to explore the role of DNM1L in the tumor microenvironment, and 22 types of immune cell profiles in STAD samples were constructed from the DNM1L expression data downloaded by TCGA." (PMID 39507763, 2024). "CIBERSORT analysis indicated that increased DNM1L expression may affect the infiltration of immune cells in the tumor microenvironment." (PMID 39507763, 2024). "Moreover, three types of tumor-infiltrating immune cells were negatively correlated with the expression level of DNM1L, namely, plasma cells, T regulatory cells (Tregs), NK cells, and activated cells." (PMID 39507763, 2024). "The intersection of differential and correlation analyses was recorded to obtain five types of tumor immune-infiltrating cells, among which two types of cells were positively correlated with DNM1L expression, including follicular, helper, NK, resting, and T cells." (PMID 39507763, 2024). "Network analysis of downstream gene signatures revealed several hub genes such as SRC and DNM1L etc. which may mediating tumor promoting functions of CEACAM6." (PMID 29137373, 2017). "Therefore, the changes in DNM1L are closely related to tumor development." (PMID 39507763, 2024). "Therefore, DNM1L affects the immunoreactivity of the tumor microenvironment." (PMID 39507763, 2024).
tumor (continued). "When glucose is lacking and galactose is utilized as a carbon source by GBM cells, there is a reprogramming of GBM metabolism, resulting in an increase in DNM1L/DRP1 expression, enhances OXPHOS activity, decreases glycolysis, and promotes tumor migration." (PMID 39350223, 2024). "Similar findings were observed in hepatocellular carcinoma cells, where increased DNM1L/DRP1 expression and augmented mitochondrial fission led to elevated OXPHOS levels, thereby promoting tumor proliferation and development." (PMID 39350223, 2024). "Therefore, we conducted repeated interventions and related experiments in GSCs to investigate the impact of DNM1L/DRP1, FIS1 and MFF expression on tumor progression in different metabolic models." (PMID 39350223, 2024).
cancer (31 papers, 2009 to 2025). A tumor composed of atypical neoplastic, often pleomorphic cells that invade other tissues. "Recent studies revealed the role of dynamin‐related protein 1 (DRP1), encoded by the DNM1L gene, in regulating the growth of cancer cells of various origins." (PMID 33152171, 2021). "To explore the hypothesis that dysregulated mitochondrial dynamics may impact drug sensitivity, we began by examining the alteration status of six canonical dynamics-regulating genes - OPA1, MFN1, MFN2, FIS1, MFF, and DNM1L (which encodes Drp1)—in human cancers." (PMID 29700304, 2018). "Published work has correlated DNM1L amplification with enhanced cell cycle gene expression and poor survival in chemoresistant and recurrent cancer samples." (PMID 39191946, 2024). "DNM1L encodes dynamin-related protein 1 (DRP1), a key protein mediating mitochondrial fission, which is upregulated in a variety of cancers and is strongly associated with tumorigenesis." (PMID 39507763, 2024). "Inhibition of mitophagy and mitochondrial fission sensitizes cancer cells to chemotherapy through DNM1L‐mediated mitochondrial fission." (PMID 34755451, 2021). "Various levels of SCNA were noted for the DNM1L gene in various cancer types, with almost 100% of TGCT patients presenting with DNM1L gene amplification." (PMID 27509055, 2016). "To investigate if elevated Drp1 expression is a result of somatic copy number amplification (SCNA) we correlated Drp1 expression with the GISTIC scores (Genomic Identification of Significant Targets in Cancer) of the Drp1 gene, DNM1L, across the cancer types." (PMID 27509055, 2016). "In this study, the differences in DNM1L expression in GC tissues and normal tissues adjacent to the cancer were analyzed by using the Cancer Genome Atlas Project (TCGA) and GEO databases, and the correlation between DNM1L and invasive GC metastasis was assessed." (PMID 39507763, 2024). "Apart from these CDK1 substrates, BCL2 apoptosis regulator (BCL2), BCL2 apoptosis regulator like 1 (BCL2L1), and dynamin 1 Like (DRP1) are phosphorylated by CDK1, mediating mitochondrial fusion and apoptosis in human cancer cells." (PMID 37311884, 2023).
neurological disorders (12 papers, 2012 to 2026). "DNM1L-associated encephalopathy is a neurological disorder with a broad spectrum of symptoms associated with mutations in the DNM1L gene." (PMID 41786974, 2026). "In recent years, with the development of sequencing, some rare neurological diseases were found to be caused by DNM1L mutations." (PMID 36908591, 2023). "DNM1L variants can lead to mitochondrial fission dysfunction and neurological disorders." (PMID 34307245, 2021). "Pathogenic DNM1l variants disrupt DRP1 oligomerization, impair GTPase-dependent constriction, and block mitochondrial fission, ultimately driving a broad spectrum of neurological disorders." (PMID 41244260, 2025). "In module-5, VCP shown interaction with 5 proteins (AKTI, CAV1, HSPA8, DNM1L, TKT) functionally associated with enzyme binding processes and most of these genes are mostly related to neoplasms disorder followed by nervous system diseases." (PMID 34918006, 2022). "Moreover, almost DNM1L-related diseases are severe neurological disorders in children and teenagers, indicating that DNM1L is required for neurological development." (PMID 36908591, 2023). "DNM1L mutations are related to various neurologic diseases in humans, and loss of DRP1‐mediated mitochondrial fission is associated with cardiomyopathy, neurologic disorders, and macrophage dysfunction in murine models." (PMID 33152171, 2021).
neurodegenerative disease (8 papers, 2013 to 2025). A disorder of the central nervous system characterized by gradual and progressive loss of neural tissue and neurologic function. "However, it is apparent that tight regulation of DNM1L is necessary to ensure proper mitochondrial function, as abnormal DNM1L activity is associated with excessive mitochondrial fission in various neurodegenerative diseases." (PMID 23977156, 2013). "Eventually, the structure-based knowledge of regulating the function of DNM1L by pharmacological means may help to target these neurodegenerative diseases successfully." (PMID 23977156, 2013).
infection (6 papers, 2016 to 2022). The state of being infected such as from the introduction of a foreign agent such as serum, vaccine, antigenic substance or organism. "Generally, the individual infection ratio of Dnm1l or Mfn1 was around 65% in both AAC alone and AAV-treated mice." (PMID 36276651, 2022).
mitochondrial disease (5 papers, 2022 to 2025). "It would therefore seem appropriate that patients with confirmed pathogenic DNM1L variants follow a cardiac surveillance programme, as is in place for other forms of mitochondrial disease, with a view to appropriate pre-emptive treatment." (PMID 35914810, 2022). "Furthermore, we conducted a literature review via PubMed (up to June 2023), using the following search string: “mitochondrial diseases” or “DRP1” or “EMPF1” associated to the keyword “DNM1L” and “children”." (PMID 38341530, 2024). "Mitochondrial disease can arise from de novo heterozygous, biallelic compound heterozygous, and homozygous recessive DNM1L variants." (PMID 35914810, 2022). "Our report provides insight into the phenotypic spectrum of DNM1L-related disorders and highlights the need to combine genetic and functional analyses to accurately diagnose rare mitochondrial diseases." (PMID 41008537, 2025). "She had a different clinical presentation compared to previously reported cases, expanding the clinical presentation of DNM1L-related mitochondrial disease." (PMID 38341530, 2024).
heart disease (3 papers, 2018 to 2022). "Since the GTPase dynamin-1-like protein (Drp1) is one main executor of mitochondria fission, specific inhibitors of Drp1 have been developed and tested in preclinical animal models of cardiac disease." (PMID 33233847, 2020).
neurodevelopmental disorder (3 papers, 2020 to 2025). A behavioral and cognitive disorder with onset during the developmental period that involves impaired or aberrant development of intellectual, motor, or social functions. "Defects in the DNM1L gene result in a complex neurodevelopmental disorder with heterogeneous symptoms affecting multiple organ systems." (PMID 32012656, 2020).
metabolic disease (2 papers, 2024 to 2025). A congenital disorder (due to inherited enzyme abnormality) or acquired (due to failure of a metabolically important organ) disorder resulting from an abnormal metabolic process. "In humans, bi-allelic loss-of-function or dominant-negative DNM1L mutations cause fatal developmental and metabolic disorders." (PMID 40792068, 2025).
DNM1L also shares sentences with these, for which no sentence is quoted: myocardial infarction (9 papers); hepatocellular carcinoma (5); ischemia (5); Cerebral ischemia (4); glioblastoma (4); microcephaly (4); Parkinson (4); Ataxia (3); colon cancer (3); Huntington disease (3); peripheral neuropathy (3); pulmonary arterial hypertension (3); type 2 diabetes (3); acute kidney injury (2); Atrophy (2); dengue virus infection (2); infertile (2); invasive breast carcinoma (2); microcytic anemia (2); multiple sclerosis (2); nasal polyps (2); neuroblastoma (2); neuropathy (2); pancreatic cancers (2); rheumatoid arthritis (2); Stroke (2); tauopathies (2); age-related hearing loss (1); alcoholic steatohepatitis (1); amyotrophic lateral sclerosis (1).
A further 68 diseases each share a sentence with DNM1L in 1 paper.